VEGFA (vascular endothelial growth factor A)
Diseases named in the same sentence as VEGFA in open-access papers (continued):
Sharing a sentence is not in itself a finding about the gene and the disease.
leukemia (111 papers, 2003 to 2026). A malignant (clonal) hematologic disorder, involving hematopoietic stem cells and characterized by the presence of primitive or atypical myeloid or lymphoid cells in the bone marrow and the blood. "High‐throughput sequencing reveals ASH2L‐K312‐lac enrichment in the genome regions encoding VEGFA, facilitating targeted recruitment of the mixed lineage leukemia complex to these loci and enhancing VEGFA expression through synergistic activation of enhancers and promoters." (PMID 40726441, 2025). "VEGFA was observed to have additive effect in inflating the risk of leukemia." (PMID 34983358, 2022). "A further analysis of VEGFA genetics in CLL subgroups defined by different clinical and molecular parameters assessed an association between the VEGFA ACG+/+ genotype with a molecular marker of aggressive leukaemia: the unmutated status of the immunoglobulin variable gene segments (IgVH)." (PMID 24971577, 2014). "Given the reported association of VEGF levels with certain clinical conditions in this leukemia, the present study evaluated whether an association exists between VEGFA genetic variability and its predictive value in determining the prognosis of CLL." (PMID 24971577, 2014). "On this line, and in agreement with our results, miR-302d and miR-302a were already considered as direct VEGFA mRNA modulators on HeLa and leukemia cells." (PMID 35624680, 2022). "In acute myeloid leukemia the genotype +936 CC/CT (rs3025039) of VEGFA have shown correlation with favorable leukemia survival." (PMID 32585853, 2020). "An autocrine VEGFA/VEGFR2 pathway opposes apoptosis in leukaemia cells through induction of the anti-apoptotic protein Bcl-258." (PMID 28383032, 2017). "The other study showed that targeting VEGFA, one of the most upregulated genes in CNS-derived leukemia cells, with the VEGF neutralizing antibody bevacizumab reduced the extent of leukemia involvement in the CNS of mice." (PMID 28491865, 2017). "A well-characterized YY1-miRNA regulatory loop involves miR-200 and miR-15/16, implicated in vascular endothelial growth factor A (VEGFA) regulation in sarcoma and drug resistance in leukaemia." (PMID 27983635, 2016). "This site was chosen as the role of VEGFA in various cancer types, including leukemia, is well documented." (PMID 26886256, 2016). "In this study, we analysed the contribution of VEGFA genetics in the clinical outcome of the leukaemia." (PMID 24971577, 2014). "Moreover, a hypoxic microenvironment coupled with the secretion of vascular endothelial growth factor-A (VEGF-A) by leukemia cells increases vascular permeability and BBB disruption, making the CNS more susceptible to invasion." (PMID 40108670, 2025). "We set the cutoff of the signal binding normalized scores (in the range of 0–1000) to 350 and identified promyelocytic leukemia (PML), cyclin T2 (CCNT2) and MYC-associated zinc finger protein (MAZ) as binding to both the +157 enhancer and the promoter of the VEGFA gene." (PMID 34316716, 2021). "In their model, leukemia-derived exosomes led to modulation of astrocytes and brain microvascular endothelial cells, resulting in upregulation of vascular endothelial growth factor A (VEGF-A) expression and sequential disruption of the BBB integrity." (PMID 32752027, 2020). "The authors speculate that VEGFA may further enhance migration of leukemia cells into the CNS through its effects on increasing endothelial, and potentially blood–brain, permeability." (PMID 28491865, 2017). "High-expressor VEGFA genotypes could increase the resistance to apoptosis, the cell motility or influence the microenvironment to generate more aggressive tumoral cells and consequently contribute to the progression of the leukaemia." (PMID 24971577, 2014). "Downregulation of HIF1α, oxidative phosphorylation, and PI3kinase pathways at EOI along with the regulators IFNG, TNF, VEGFA, IL1B in B cells is likely to impede leukemia supportive pro-inflammatory signaling." (PMID 37532715, 2023).
leukemia (continued). "Third, miR-125b facilitates the progression of leukemia by promoting the expression of oncogenic MLL-AFF9 in vivo, and it upregulates VEGFA, providing conditions conducive to the expansion of leukemic cells." (PMID 38292478, 2023). "The expression of VCAM1, VEGFA, PECAM1, and ICAM1, which promote leukemia cells to cross the BBB, was studied by RT-PCR." (PMID 35256780, 2022). "On the other hand, the analysis of leukaemia cell/CP fibroblast co‐cultures also showed that CD19+ blasts expressed IL1B, TGFB1, VEGFA, and the metalloproteinase ADAM10, and this expression was significantly upregulated in the presence of CP fibroblasts." (PMID 32686161, 2020). "Furthermore, FLT-1 is generally expressed in pediatric ALL and VEGFA/FLT-1 signaling enhances the migration and survival of leukemia." (PMID 34980027, 2022). "In addition to the hypothetical use of VEGFA SNPs to predict the clinical outcome for CLL, these polymorphisms could be used as markers of clinical efficacy for chemoimmunotherapy with novel agents targeting VEGF or its receptor (VEGFR) to prevent leukaemia progression." (PMID 24971577, 2014).
thyroid cancer (110 papers, 2007 to 2025). "In addition, sex-specific effects of VEGFA SNPs, ethnic differences and gene-environment interaction in the association between VEGFA single nucleotide variants and thyroid cancer merit further investigation." (PMID 28178662, 2017). "It is noteworthy that the last study showed novel loci containing genes that were previously implicated in thyroid cancer (e.g., HES1, SPATA13, DIRC3, ID4) and a positive association of TSH with VEGFA expression, therefore angiogenesis." (PMID 39767631, 2024). "We only indicated that PLAT can inhibit thyroid cancer angiogenesis through VEGFa/VEGFR2 and other signaling ways also need to be explored." (PMID 38186223, 2024). "And when the exogenous human VEGFA (hVEGFA) was increased, the inhibition of PLAT was restrained, suggesting that PLAT inhibits thyroid cancer angiogenesis through VEGFa." (PMID 38186223, 2024). "Transfection of miR-205 into thyroid cancer cells resulted in downregulation of VEGFA with downstream inhibition of cell cycle progression and increased apoptosis." (PMID 37020673, 2023). "In thyroid cancer, miR-205 is significantly under-expressed compared to normal thyroid controls, and the under-expression of miR-205 resulted in over-expression of VEGFA." (PMID 37020673, 2023). "The subsequent results showed that oridonin inhibited angiogenesis and VEGFA expression in thyroid cancer cells by tube formation assay, western blot and ELISA assay." (PMID 35813296, 2022). "In this study, the data revealed that LKB1 overexpression attenuated the HUVEC recruitments and decreased the expression of VEGFA in thyroid cancer cells, as evidenced by HUVEC migration assay, western blot and ELISA assay." (PMID 35912012, 2022). "To further confirm the role of LKB1 in thyroid cancer angiogenesis, we detected a crucial regulatory gene of tumor angiogenesis, VEGFA." (PMID 35912012, 2022). "Reduction of VEGFA by over-expression of miR-34b suppressed thyroid carcinoma cell growth, metastasis, and angiogenesis." (PMID 34703899, 2021). "VEGFA was reported to be involved in miR-34b-5p-mediated angiogenesis and cell growth of thyroid carcinoma." (PMID 34703899, 2021). "The TCGA (The Cancer Genome Atlas Program) thyroid cancer dataset showed that VEGFA and NFE2L2 were highly expressed in normal tissue (n = 59) when compared with the primary tumor (n = 505)." (PMID 32824922, 2020). "Increasing endothelial cells is the first step in goiter formation, which exhibits levels of VEGFA expression similar to those observed in some types of thyroid cancer." (PMID 32824922, 2020). "In this study, we selected five tag SNPs in VEGFA to investigate the association between thyroid cancer (PTC and NG) and VEGFA polymorphisms in Northern Han Chinese." (PMID 28178662, 2017). "In our study, the findings demonstrated that oridonin could modulate the protein level of VEGFA to repress thyroid cancer angiogenesis, as evidenced by the western blotting assay and ELISA assay." (PMID 35813296, 2022). "Taken together, these data strongly suggested that oridonin could suppress VEGFA expression via JAK2/STAT3 pathway in thyroid cancer cells." (PMID 35813296, 2022). "Furthermore, overexpression of LKB1 attenuated HUVEC recruitment, decreased the expression of VEGFA and inhibited the formation of new vessels in thyroid cancer cells." (PMID 35912012, 2022). "Corroborating with our results, earlier studies have shown that the expression of the VEGFA is higher in thyroid cancer, and may be crucial for the development of goiter, since the proliferation of endothelial cells precedes that of thyroid cells." (PMID 32824922, 2020). "The only previous study that investigated miR-205 expression in thyroid neoplasia suggested that miR-205 overexpression might have a potential tumor suppressive role, which could be exerted through miR-205 binding to 3-UTR of vascular endothelial growth factor A (VEGFA) protein in thyroid cancer." (PMID 35282462, 2022).
thyroid cancer (continued). "Furthermore, ELISA data indicated that overexpressing LKB1 could decrease the secretion of VEGFA in these two thyroid cancer cells." (PMID 35912012, 2022). "Additionally, there is no report on the association between thyroid cancer and VEGFA polymorphisms in the Chinese population." (PMID 28178662, 2017). "Thus, we believe that PLAT may inhibit thyroid cancer angiogenesis through VEGFa/VEGFR2." (PMID 38186223, 2024). "What’s more, PLAT in thyroid cancer cells can inhibit HUVEC proliferation and tube formation through VEGFa/VEGFR2, which is a new finding in thyroid cancer." (PMID 38186223, 2024). "High expression of VEGFA and VEGFC showed favorable responses to various drugs, including BLU-667, which abrogates RET signaling, an oncogenic driver in liver and thyroid cancers." (PMID 37852616, 2023). "Furthermore, hsa _circ_0011058 and hsa_circ_0082003 (circ0002111) indirectly promote the translation of angiogenic proteins (VEGFA and FGF) by upregulating YAP1 and HMGB1 in thyroid cancers, respectively, thereby promoting angiogenesis in TCs." (PMID 38316961, 2024). "Deregulation of VEGFA (Vascular Endothelial Growth Factor A) and NFE2L2 (Nuclear Factor (Erythroid-derived 2)-Like 2), involved in angiogenesis and oxidative stress, can lead to thyroid cancer progression." (PMID 32824922, 2020).
neuroblastoma (107 papers, 2006 to 2025). Neuroblastoma (NB) is the most common solid, extracranial childhood tumor. "In neuroblastoma, cancer cells secrete VEGFA, which is involved in the VEGFA/VEGFR2 signaling pathway and promotes vascularization, into the microenvironment." (PMID 38474195, 2024). "VEGFA, encoding the vascularization growth factor VEGF, is highly expressed in various neuroblastoma cell lines." (PMID 37958729, 2023). "VEGF/VEGFA is the most common pro-angiogenic factor found in neuroblastoma tumors, but many other factors like fibroblast growth factor (FGF), platelet-derived growth factor (PDGF) are reported in NB." (PMID 32722460, 2020). "Hypoxia was a strong inducer of VEGFA mRNA in the NB1691 neuroblastoma cell line, while ER stress had little effect on VEGFA levels." (PMID 20824063, 2010). "Since neuroblastomas are highly hypoxic, these data suggest that BAP31 enhances the hypoxic and nutrient deprivation-dependent GAL-3 and VEGFA up-regulation." (PMID 38474195, 2024). "In our study, both VEGFA and GAL-3 positively correlated with BAP31 overexpression and knockdown in SH-SY5Y neuroblastoma cells." (PMID 38474195, 2024). "Common targets for both HIFs include vascular endothelial growth factor (VEGFA) and RGS4 gene coding for a protein regulating signaling activity of G-proteins, which enhanced expression is specific for hypoxic neuroblastoma cells." (PMID 32722310, 2020).
Alzheimer disease (106 papers, 2011 to 2026). A progressive, neurodegenerative disease characterized by loss of function and death of nerve cells in several areas of the brain leading to loss of cognitive function such as memory and language. "VEGFA polymorphism has also shown promise as a protective marker for Alzheimer’s disease." (PMID 37189449, 2023). "The majority of vascular transcriptional changes occur in pericytes, with SMAD3 upregulated in Alzheimer’s disease pericytes having the highest number of ligands including VEGFA, which is downregulated in Alzheimer’s disease astrocytes." (PMID 41465272, 2025). "Of the vascular molecular targets predicted to interact with astrocytic ligands, SMAD3, upregulated in Alzheimer’s disease pericytes, has the highest number of ligands including VEGFA, downregulated in Alzheimer’s disease astrocytes." (PMID 38902234, 2024). "Our bioinformatics analysis revealed four key differential genes—ASS1, HDAC2, SIRT3, and VEGFA—as Co-DEGs in patients with Alzheimer’s disease (AD) and OSA." (PMID 39081807, 2024). "Augmented VEGFA levels in cerebrospinal fluid and plasma have been reported in Alzheimer’s disease and vascular dementia patients probably as a consequence of hypoperfusion and hypoxia." (PMID 35625687, 2022). "Altered levels of VEGFA have been related to several neurodegenerative and neurological disorders, such as Alzheimer’s disease, vascular dementia and stroke." (PMID 35625687, 2022). "Moreover, VEGFA therapy may be beneficial in slowing the progression of Alzheimer’s Disease (AD) and Parkinson’s Disease (PD), where vascular weakness further exacerbates the disease through further neuronal death." (PMID 37189449, 2023). "In parallel, biological markers involved in both hippocampal neurogenesis and Alzheimer’s disease, such as BDNF, VEGFA and IGF-1, were evaluated in aged mice." (PMID 28218311, 2017). "Here, we detect vast transcriptome changes in Alzheimer’s disease at the gliovascular-unit, prioritize perturbed pericytic SMAD3-astrocytic VEGFA interactions, and validate these in cross-species models to provide a molecular mechanism of blood-brain-barrier disintegrity in Alzheimer’s disease." (PMID 38902234, 2024). "We reported the VEGFA, AChE, and DRD2 genes as the top correlated genes to memory disorders and Alzheimer’s disease in our gene set using a theoretical computerized chemical–biological relationship between identified metabolites from OEP extract and Alzheimer’s disease." (PMID 36557216, 2022). "Using pharmacology networking to specify the targets of the identified compounds with a relationship to Alzheimer’s disease, it was possible to identify the VEGFA, AChE, and DRD2 genes as the top correlated genes to Alzheimer’s disease with 8, 8, and 6 interactions in the same order." (PMID 36557216, 2022). "In addition, in the common carp liver, the KEGG pathway analysis showed that Alzheimer’s disease was related to genes INSR, GAPDHS, BAX, DHCR24, PPARG, ENO1, and VEGFA." (PMID 35741857, 2022).
heart failure (106 papers, 2009 to 2026). Inability of the heart to pump blood at an adequate rate to meet tissue metabolic requirements. "VEGFA administration has been explored as a pro-angiogenic therapy for cardiovascular diseases including heart failure for several years, but with little success." (PMID 39612288, 2024). "The upregulation of human miRNA-377 represses the synthesis of vascular endothelial growth factor A (VEGFA) and, as a consequence, reduces angiogenesis, which has been associated with heart failure." (PMID 34445712, 2021). "Previous studies have shown that the VEGFA-KDR pathway is closely related to heart failure." (PMID 38020087, 2023). "VEGFA participates in the SIRTI/FOXO3a/MnSOD pathway and inhibits mitochondrial oxidative stress, ameliorating cardiac dysfunction in rats with heart failure." (PMID 38883603, 2024).
Blindness (103 papers, 2008 to 2026). Blindness is the condition of lacking visual perception defined as a profound reduction in visual perception. "Vascular endothelial growth factor-A (VEGF-A) is known to play a crucial role in ocular angiogenesis, which is a predominant cause of blindness in various clinical conditions." (PMID 37953270, 2023).
osteoarthritis (102 papers, 2006 to 2026). A noninflammatory degenerative joint disease occurring chiefly in older persons, characterized by degeneration of the articular cartilage, hypertrophy of bone at the margins and changes in the synovial membrane. "Overexpression of ERRγ has been shown to increase the expression of matrix metalloproteinase (MMP9) and vascular endothelial growth factor A (VEGFA) in chondrocytes, resulting in extracellular matrix degradation and vascular proliferation in osteoarthritis." (PMID 35954227, 2022). "After careful review of the recent literature, results for vascular endothelial growth factor A (VEGFA) and interleukin 1 beta (IL1β) were diametrically opposite to those in our osteoarthritis microarray analysis, so we excluded them." (PMID 30560591, 2019). "Based on the previous study, we then evaluate the expression distribution of the MMP, VEGFA, SPI1, and IRF8 in synovial tissues of patients with osteoarthritis." (PMID 36960385, 2023). "The single-cell RNA sequencing analysis was used to evaluate the expression distribution of the MMP, VEGFA, SPI1, and IRF8 in synovial tissues of patients with osteoarthritis." (PMID 36960385, 2023). "The verification result showed that the expression levels of IL6, VEGFA, JUN, IL-1β, and ATF3 were significantly increased in osteoarthritis samples (p < 0.05)." (PMID 30186872, 2018). "Puerarin, ferroptosis, and osteoarthritis share four targets: PLIN2, PTGS2, VEGFA, and IL6." (PMID 37548663, 2024).
myocardial ischemia (101 papers, 2010 to 2026). A disorder of cardiac function caused by insufficient blood flow to the muscle tissue of the heart. "Danshensu improved coronary flow, heart rate, and left ventricular developed pressure in isolated rat hearts myocardial ischemia model, while Danshen increased HIF1α and VEGFA expression, improving cardiac function and angiogenesis in myocardial ischemia mice." (PMID 39273041, 2024). "Recent studies indicated that VEGFA released from different types of stem cells, including MSCs, have the ability to treat various human diseases, such as myocardial ischemia, by regulation of angiogenesis." (PMID 32616068, 2020). "In the context of myocardial ischemia, it was shown that modRNA for vascular endothelial growth factor A (VEGF-A) exerted pro-regenerative effects in a mouse model." (PMID 33003617, 2020). "Our transcriptional data provide evidence that significantly higher levels of hypoxia-related and proangiogenic genes (HIF1a, VEGFA, FGF2, eNOS, SOX17, and LRG1) promote neovascularization at the site of increased cardiac ischemia." (PMID 36371548, 2023). "Anti-VEGFA therapy could be a therapeutic strategy for diabetic kidneys, but studies have shown that an excessive inhibition could promote proteinuria; therefore, inhibitors of VEGF could result in: cardiac ischemia, cardiac dysfunction, and an increase in blood pressure." (PMID 35453821, 2022). "In myocardial ischemia, lack of SGK1 blunts the phosphorylation of SGK1 target protein NDRG1 and compromises the up-regulation of transcription factor NF-κB and its target protein, VEGF-A (vascular endothelial growth factor A)." (PMID 31225494, 2018).